ROPN1 (rhophilin associated tail protein 1)
Description:
Important for male fertility. With ROPN1L, involved in fibrous sheath integrity and sperm motility, plays a role in PKA-dependent signaling processes required for spermatozoa capacitation.
Synonyms: CT91; ROPN1A; ODF6; ropporin; RHPNAP1
Tractability: PROTAC: UniProt records ubiquitination sites on it.
Gene: Protein-coding gene on chromosome 3 (123,968,521 to 123,992,178, reverse strand). Ensembl gene ENSG00000065371.
Subcellular location: Cell projection, cilium, flagellum
Subcellular location (Human Protein Atlas): Principal piece
Pathways (Reactome):
Signal Transduction: RHO GTPases Activate Rhotekin and Rhophilins
Gene Ontology:
Molecular function: identical protein binding; protein binding
Biological process: cilium organization; flagellated sperm motility; protein localization to cilium; sperm capacitation
Cellular component: cytoplasm; nucleus; motile cilium
Genetic constraint (gnomAD): Loss-of-function variants: 14 observed, 16.93 expected, observed/expected ratio (o/e) 0.83, 90% interval 0.55 to 1.29. The upper end of that interval is the gene's LOEUF score, 1.29, which puts it in group 5 of 6, group 1 being the genes least tolerant of losing a copy. Missense variants: 166 observed, 203.98 expected, observed/expected ratio (o/e) 0.81, 90% interval 0.72 to 0.93. Synonymous variants: 74 observed, 83.89 expected, observed/expected ratio (o/e) 0.88, 90% interval 0.73 to 1.07.
Homologues: Orthologues: chimpanzee ROPN1 (99% identical), dog ROPN1 (86% identical), rat Ropn1 (84% identical), mouse Ropn1 (83% identical). Paralogues in human: ROPN1B (96% identical), ROPN1L (39% identical).
Diseases named in the same sentence as ROPN1 in open-access papers:
ROPN1 is named in the same sentence as 10 diseases in open-access papers, as found by Europe PMC text mining. Sharing a sentence is not in itself a finding about the gene and the disease. The quoted sentences say what the papers report.
breast carcinoma (4 papers, 2015 to 2025). "LINC02188 has been shown to be upregulated in triple-negative breast cancers, while PROM1, ROPN1, GABRP, and FDCSP were previously associated with a cancer stem cell signature in a basal-like breast cancer phenotype." (PMID 33525353, 2021). "Subsequently, we further narrowed down the eight candidate genes (TRIM47, SPHK1, RGMA, ROPN1B, LARP6, ROPN1, NPM2 and LPL) that are shared in TNBC compared to ER+ and HER2+ breast cancer subtypes in cancer cells." (PMID 40635123, 2025). "Noteworthy, the CM1 list revealed a set of probes for which little literature exists in relation to breast cancer subtypes: CDCA5, CCL15, COL17A1, GLYATL2, ROPN1, LINC00993 and C6orf211." (PMID 26132585, 2015).
multiple myeloma (3 papers, 2015 to 2021). "ROPN1 has been demonstrated to induce autoantibodies in patients with prostate cancer and multiple myeloma." (PMID 29190970, 2017).
asthenospermia (2 papers, 2019 to 2021). "CABYR and ROPN1 mRNA were significantly downregulated in asthenozoospermia patients' samples and a positive correlation was confirmed between the expression of the two genes, indicating that the co-expression of CABYR and ROPN1 was a prerequisite for normal sperm motility and flagellar function." (PMID 33746583, 2021).
triple-negative breast carcinoma (2 papers, 2020 to 2021). An invasive breast carcinoma which is negative for expression of estrogen receptor (ER), progesterone receptor (PR), and human epidermal growth factor receptor 2 (HER2). "It has been shown that actin SF plays an essential role in promoting migration and metastasis of triple negative breast cancer in which RhoA can be activated by the interaction between Rhophilin-associated tail protein 1 (ROPN-1) and rhophilin-1 to enhance actin SF formation." (PMID 33158289, 2020).
acute myeloid leukemia (1 paper, 2016). Acute myeloid leukemia (AML) is a group of neoplasms arising from precursor cells committed to the myeloid cell-line differentiation. "For instance, promoter methylation of GAGE1 has been reported in PCa cell lines, while ROPN1 has been found to be expressed in a subset of acute myeloid leukemia (AML) patients." (PMID 26885621, 2016).
melanoma (1 paper, 2021). A malignant, usually aggressive tumor composed of atypical, neoplastic melanocytes. "We therefore hypothesised that this may also be the case in melanoma and aimed to investigate the expression and immunogenicity of ROPN1 and ROPN1B." (PMID 33918976, 2021). "We tested the gene expression levels of ROPN1 and ROPN1B (96% sequence homology with ROPN1) in a panel of melanoma cell lines generated in-house." (PMID 33918976, 2021). "In this study, gene-expression profiling of a large panel of early-passage melanoma cell lines identified ROPN1 and ROPN1B as being highly expressed in melanoma tumour samples (ROPN1: 81.8%, ROPN1B: 83.6%), more so than CTAG1 (36.4%)." (PMID 33918976, 2021). "We further investigated ROPN1, ROPN1B and CTAG1B gene expression across different stages of disease and genders in melanoma." (PMID 33918976, 2021). "Similarly, gene expression of ROPN1 and ROPN1B was also commonly detected in a melanoma patient cohort accessed via the TCGA (ROPN1: 98.9%, ROPN1B: 98.7% vs. CTAG1B: 68.2%)." (PMID 33918976, 2021). "The expression of differentiation antigens that are commonly present and have been previously used as immunological targets in melanoma, namely, TYR (tyrosinase) and MLANA (Melan-A/MART1), were compared with CTAG1A and ROPN1 or ROPN1B in our panel of melanoma cell lines." (PMID 33918976, 2021). "We further evaluated the gene expression levels of ROPN1, ROPN1B, CTAG1B (identical gene copy to CTAG1A for which no gene expression data is available), TYR and MLANA in 472 additional melanoma samples using data accessible via The Cancer Genome Atlas (TCGA)." (PMID 33918976, 2021).
metastatic melanoma (1 paper, 2021). A melanoma that has spread from its primary site to another anatomic site. "Here, we show that Ropporin-1 (ROPN1) and 1B (ROPN1B), cancer restricted antigens, are highly expressed and immunogenic, inducing humoral immunity in patients with advanced metastatic melanoma." (PMID 33918976, 2021).
cancer (5 papers, 2017 to 2025). A tumor composed of atypical neoplastic, often pleomorphic cells that invade other tissues. "In the second family in which MPT21 and two relatives were tested, we found four LP variants (BPIF1, BCORL1, ROPN1, and PRSS3) and four other cancer-related genes (TUBB2B, CFAP54, PSG2, and SIRPB1)." (PMID 39408606, 2024). "Variants in four genes (ROPN1, PRSS3, BPIFB1, and BCORL1) were detected in all individuals from Family 2, while four (TUBB2B, CAFAP54, PSG2, and SIRPB1) were exclusive of the MPT21 index case and her relative with cancer (MPT21.2)." (PMID 39408606, 2024). "In addition, FSIP1 can bind to and activate cancer/testis antigen proteins (including CABYR, SPA17, AKAP3, AKAP4, and ROPN1) in the fibrous sheath in tumor cells, in turn promoting cancer progression." (PMID 28086239, 2017).
tumor (3 papers, 2015 to 2021). "Furthermore, ROPN1 is mostly down-regulated in tumor samples in comparison to normal samples (FDR corrected test p-value < 8.4e-14, the ratio of the average expression in the tumor samples to that in the adjacent normal samples = 0.14)." (PMID 26618778, 2015).
ROPN1 also shares sentences with these, for which no sentence is quoted: prostate carcinoma (1 paper).